RNVU1-26 (RNA, variant U1 small nuclear 26)
Gene: Small nuclear RNA gene on chromosome 1 (144,523,860 to 144,524,021, reverse strand). Ensembl gene ENSG00000275291.
Gene Ontology:
Molecular function: pre-mRNA 5'-splice site binding
Biological process: mRNA 5'-splice site recognition
Cellular component: U1 snRNP
Homologues: Orthologues: chimpanzee U1 (82% identical), chimpanzee U1 (81% identical), rabbit U1 (59% identical), zebrafish U1 (42% identical). Paralogues in human: RNVU1-24 (99% identical), RNVU1-25 (98% identical), U1 (98% identical), RNU1-1 (75% identical), RNU1-2 (75% identical), RNU1-27P (75% identical), RNU1-28P (75% identical), RNU1-3 (75% identical), RNU1-4 (75% identical), RNVU1-18 (75% identical), RNVU1-29 (75% identical), RNVU1-31 (75% identical), and 134 more.